INS (insulin)
Diseases named in the same sentence as INS in open-access papers (continued):
Sharing a sentence is not in itself a finding about the gene and the disease.
diabetes (continued). "For patients suffering from T2D, lifestyle intervention and metformin, a medication that increases insulin sensitivity, were shown to decrease the incidence of diabetes by 58% and 31%, respectively." (PMID 37761009, 2023). "Diabetes mellitus (DM) is a metabolic disorder characterized by hyperglycemia as a result of abnormal insulin secretion and insulin action." (PMID 37149604, 2023). "Overall, the "first-in-class" plant-derived insulin mimetic aM1 shows high promise as a lead and approach for developing a new class of drugs for diabetes." (PMID 37715850, 2023). "When our body is unable to create insulin or is unable to use the insulin that is produced by our bodies, diabetes results." (PMID 37958014, 2023). "We also showed that in adults at risk for diabetes or with early type 2 diabetes, the MFDM powder formula produced significantly less glucose and insulin responses compared with a commercially available standard formula (SF)." (PMID 37293492, 2023). "Patients that experienced long-term T2D remission presented a statistically significant shorter duration of diabetes, lower preoperative fasting glucose and HbA1c, and less use of insulin therapy, when compared with other two groups." (PMID 37085634, 2023). "On the other hand, in the WJMSC-CM treated group and insulin-treated group, the total volume of the right hippocampus was significantly higher than in the untreated diabetes group (P < 0.05)." (PMID 37081849, 2023). "Other drugs used in management of diabetes mellitus (other oral drugs and insulin) were less available than metformin." (PMID 36788557, 2023). "Recent data have suggested that insulin-requiring diabetes mostly contributes to the overall increase of thromboembolic risk in patients with atrial fibrillation (AF) on warfarin." (PMID 35976428, 2023). "Diabetes disturbed general parameters of β-cell mass (islet size, β-cell abundance and distribution) and health (insulin and PDX-1 expression), increased lipid peroxidation in islet cells, and phagocytic removal of iron-containing material." (PMID 37600723, 2023). "Since its discovery over 100 years ago, insulin has been used as a life-saving treatment for people with diabetes." (PMID 37104015, 2023). "Type 2 diabetes mellitus (T2DM) occurs more frequently in obese individuals than in persons with normal weight and is associated with impairment in insulin secretion and activity." (PMID 36678160, 2023). "The insulin resistance with hyperinsulinemia is usually deleterious for the liver, and exogenous insulin in patients with type 2 Diabetes Mellitus is often worthwhile." (PMID 38223606, 2023). "The correlation between glucose CV and age, BMI, diabetes duration, daily insulin dosage, FBG, HbA1c, FCP, 2hCP, spermidine, L-methionine, and trehalose was analyzed using linear regression analysis by employing a stepwise procedure." (PMID 36771224, 2023). "Randomly, 35 male Sprague Dawley rats weighing 260–300 g were allocated into five groups: control, diabetes, and three diabetic groups treated with insulin, WJMSC-CM, and DMEM." (PMID 37081849, 2023). "Diabetes mellitus is a metabolic disorder characterized by hyperglycemia due to impaired insulin secretion, impaired insulin action, or both." (PMID 37512017, 2023). "Diabetes mellitus is a disorder characterized by decreased metabolic function as a result of defective insulin production and response, leading to serious health complications." (PMID 36751181, 2023). "This study aimed to explore and quantify the categorical patterns of social support observed in a DOC, taking into consideration users’ different diabetes stages, including prediabetes, type 2 diabetes (T2D), T2D with insulin treatment, and T2D remission." (PMID 36607714, 2023). "Diabetes mellitus (DM) is a chronic, metabolic condition marked by defects in insulin production, action, or both." (PMID 38313182, 2023).
diabetes (continued). "The IPSCs were differentiated into beta cells, and it was observed that the corrected WFS1 IPSC-derived beta cells showed strong dynamic insulin secretion and reversed streptozocin-induced diabetes following transplantation into mice." (PMID 37371672, 2023). "This novel insight offers a promising foundation for future studies delving into the multifaceted interconnections of diabetes, insulin resistance, and GS." (PMID 38333726, 2023). "This proves that in animals with STZ-induced diabetes, baicalin can effectively improve the structure and endocrine function of the insulin-secreting cells." (PMID 38203600, 2023). "In animal models and clinical trials, using probiotics to treat diabetes lowered fasting blood glucose and serum insulin levels." (PMID 37554593, 2023). "In patients with diabetes mellitus, insulin administration promoted inhibition of Wnt5a and JNK signaling while the addition of A23187 resulted in eNOS activation by enhancing nitric oxide production in endothelial cells." (PMID 36984870, 2023). "Our patients, however, were older on average and at higher risk for hypoglycemia, which is more common in the elderly, with longer duration of diabetes and in insulin-treated people." (PMID 36882852, 2023). "Other qualitative studies of insulin-treated diabetes and T1D in SSA report similar themes consistent with this study." (PMID 37291520, 2023). "Diabetes is a long-term condition that impairs the pancreas’ ability to generate insulin as well as how the body uses it." (PMID 37315063, 2023). "About 80% of cirrhotic individuals have glucose intolerance, 60% to 80% of them are insulin resistant, and 20% go on to develop overt diabetes mellitus." (PMID 37255908, 2023). "The BBB permeability of insulin is reduced by obesity, inflammation, hyperglycemia, diabetes, and dyslipidemia." (PMID 36834911, 2023). "There are several studies demonstrated the effects of natural products in diabetes management by improving insulin sensitivity and reducing its resistance." (PMID 37408757, 2023). "Myocardial ketone metabolism is especially critical when there is decreased availability of other substrates, as found in the diabetes-exposed and insulin-resistant heart, which has impaired glucose uptake and reduced metabolic flexibility." (PMID 36835096, 2023). "Clinical experience has been consistent with this notion as large doses of insulin are frequently needed to manage patients in the hospital with diabetes." (PMID 36857969, 2023). "Those associations were not changed after adjustment for age, gender, BMI, blood pressure, habits of smoking and alcohol drinking, history of diabetes, and histories of medication therapy using insulin and anticoagulants." (PMID 38188971, 2023). "Regarding long-term outcomes of patients, only one HR patient required long-term insulin replacement for persistent diabetes." (PMID 40303251, 2023). "Dorzagliatin restored the hepatic GK expression in diabetes rats, increased the numbers of insulin-secreting cells in the pancreas, and improved glycemic control after 28-day treatment." (PMID 36918550, 2023). "Nine participants (56%) had one or more medical conditions other than diabetes and 11 participants (69%) were taking medications other than insulin, with the most common being cholesterol-lowering medications." (PMID 37432920, 2023). "As schools support type 1 diabetes management, some centers have piloted interventions in the school setting, including school nurse administration of long-acting insulin, diabetes education in school, telemedicine, and care coordination." (PMID 37929231, 2023). "The transplanted iPSC-derived islets successfully produced insulin and effectively reduced high glucose levels, suggesting their therapeutic potential for treating diabetes." (PMID 38017433, 2023). "In Belgium, national data on renal insufficiency are available for a subset of individuals with diabetes using 3 or more insulin injections per day or pump therapy." (PMID 36795662, 2023).
diabetes (continued). "When the body's need for glucose surpasses the supply available, there is an increased risk of hypoglycemia, especially in individuals with diabetes who are taking insulin or other diabetes medications." (PMID 38169925, 2023). "Diabetes mellitus (DM) has been related to increased expression of ACE2 receptors on these insulin-secreting pancreas cells." (PMID 36124445, 2023). "In groups with type 2 diabetes mellitus and obesity, platelets exhibited a robust response to insulin." (PMID 37960200, 2023). "Diabetes mellitus is a metabolic syndrome with multiple etiology in which there will be a disturbance in the insulin secretion or insulin action or both; that results in chronic hyperglycaemia due to defects in carbohydrate, protein and fat metabolism." (PMID 37255826, 2023). "In people living with diabetes, the insulin-dependent pathways are impaired, yet the insulin-independent pathways, like the AMP-activated protein kinase (AMPK) pathway, remain intact." (PMID 37606407, 2023). "60% were male, the mean age was 37.4 ± 13.4 years old, the mean diabetes duration was 17.7 ± 10.6 years and 40.6% percent were using an insulin pump (all patients were using stand-alone systems)." (PMID 38008747, 2023). "The combined impairment of insulin secretion and function is pivotal in the progression of hyperglycemia as is the case in prediabetes to diabetes." (PMID 37383391, 2023). "In the pharmacological treatment of diabetes, insulin, sulfonylurea derivatives, glinides, biguanide derivatives, α-glucosidase inhibitors, and glitazones are used." (PMID 37763199, 2023). "Type 1 diabetes mellitus (T1DM) is defined by autoimmune damage to pancreatic beta cells that affects the functioning generation of insulin, which regulates blood glucose levels (five percent of all kinds of diabetes)." (PMID 36717857, 2023). "Diabetes mellitus is a disorder in which an alteration in the carbohydrate metabolism predominates, resulting from a decrease in pancreatic insulin secretion, a decreased peripheral sensitivity to insulin, or a variable combination of both." (PMID 37836433, 2023). "The diabetes severity score parameters included the number of oral hypoglycemic agents, diabetes duration, insulin use, or presence of chronic kidney disease, diabetic retinopathy, or cardiovascular disease." (PMID 36707543, 2023). "The goal of physical exercise is to achieve blood sugar level regulation, improve the action of insulin, improve the metabolism of protein and fat, avoid complications of diabetes, and increase life quality and expectancy." (PMID 37546053, 2023). "Clinical studies on human volunteers have been conducted for a variety of biomolecules, such as glucagon and insulin for diabetes, aflibercept and acetonide for diabetic macular edema, and parathyroid hormone for osteoporosis." (PMID 36678906, 2023). "This classification was based on preoperative HbA1c, duration of T2DM, number of diabetes medications, and insulin use before surgery." (PMID 37241216, 2023). "Evidence from several studies reported that self-monitoring of BG using different methods showed favorable clinical outcomes in terms of glycemic control even in patients with diabetes who are treated with insulin." (PMID 37097724, 2023). "The Scc tool is a simple tool enabling accurate insulin dosing to all diabetes patients treated with basal and bolus insulin." (PMID 36750449, 2023). "Diabetes is characterized by persistent hyperglycaemia and attributed to malfunctioning in insulin secretion, resistance to insulin peripheral actions, or both." (PMID 37924066, 2023). "Hospitalization rates and length of stay have been observed to be correlated with serum levels of HbA1c, insulin demand, duration of diabetes, and presence of complications, and the worse these factors, the worse will be the outcome of the patient." (PMID 36984473, 2023).
diabetes (continued). "Prior to bariatric surgery, 47 patients (36.1%) were on oral medications, while the majority (79 patients, 60.7%) required both oral prescriptions and insulin to manage their diabetes." (PMID 36827391, 2023). "Future studies using biomarkers reflecting inflammatory states, impaired insulin signaling, and hyperinsulinemia are needed to fully assess the role of these pathways in explaining the effects of overweight/obesity on diabetes." (PMID 36767197, 2023). "Mischinsuline von NPH-Insulin mit kurzwirksamen Insulinanaloga ermöglichen ein Weglassen des Spritz-Ess-Abstandes (siehe Leitlinie „Diagnostik und Therapie des Typ 1 Diabetes mellitus“)." (PMID 37101024, 2023). "Insulin therapy should be considered as a first-line therapy for patients already diagnosed with diabetes who require corticosteroid therapy due to the rapid action of insulin compared to oral antidiabetic agents." (PMID 37628857, 2023). "Among participants on insulin monotherapy in 2013 and alive by the end of the study period, the use of ≥1 diabetes therapy in addition to insulin increased to 13.7% for men and 14.6% for women in 2019." (PMID 37874829, 2023). "Other baobab bioactive compounds such as gallic acid can also act beneficially on diabetes through glucose and insulin homeostasis improvement." (PMID 37432337, 2023). "Except for causing obesity, OVX also causes hyperglycemia and raises the risk of insulin resistance and even diabetes in females, while liver-derived FGF21 is a pivotal factor to regulate both glucose metabolism and insulin sensitivity." (PMID 37834368, 2023). "The duration of diabetes was 6.4 ± 4.1 years, all patients were treated with oral hypoglycemic drugs, and 12 patients were treated with insulin." (PMID 36604458, 2023). "Measurement of glucose levels in the blood after a period of fasting must have surpassed 100 mg/dL for it to be regarded as an indicator for the onset of metabolic syndrome, or hypoglycemic therapy using oral diabetes medications or insulin must be present." (PMID 38248733, 2023). "In parallel, developments in diabetes technology like continuous glucose monitoring systems, insulin pumps, telemedicine and precision medicine have advanced diabetes management." (PMID 36845885, 2023). "Insulin type, hypoglycemia awareness status, insulin device satisfaction and levels of diabetes distress are potentially modifiable in the clinical setting." (PMID 37160785, 2023). "There is also another report from India where insulin secretory capacity in lean/low BMI adult individuals with diabetes was lowest when compared with individuals with T2D or controls but higher than those with type 1 diabetes." (PMID 37601212, 2023). "In 1921, Banting and Best successfully isolated insulin, a hormone produced by the pancreas, leading to a life-saving treatment for diabetes." (PMID 37927670, 2023). "Further, lack of resources restricted health-professional support provisions to dietitian-only with limited support from a diabetes educator to provide specific insulin titration advice." (PMID 37432920, 2023). "Of the seven patients with known diabetes, only three had HbA1c < 8.0% and four had poor metabolic control despite antidiabetic therapy, including insulin." (PMID 37529514, 2023). "It is suggested that preserving insulin secretion is important for both the development and improvement of diabetes." (PMID 37424863, 2023). "Comparing our findings with existing literature, numerous studies have elucidated the benefits of telemedicine in diabetes management, especially for insulin-dependent patients." (PMID 38077677, 2023). "The glycemic control of secondary diabetes, either through a hygienic–dietetic regime, oral antidiabetics or insulin therapy, is largely managed according to the same rules and principles as the therapy for primary forms of diabetes." (PMID 37628857, 2023).
diabetes (continued). "Meanwhile, the DNT measured numeracy skills for diabetes, such as food label interpretation, insulin dose calculation based on blood glucose level, and carbohydrate corrections." (PMID 37858279, 2023). "The facts of injectable amyloidosis, which tend to increase in recent years, accompanying the treatment of patients with diabetes mellitus with insulin and its analogues, have been established." (PMID 36835194, 2023). "Several scientific societies recommend using trend arrows for bolus insulin adjustments for diabetes care." (PMID 36900956, 2023). "The artificial pancreas, a technology that minimizes user input by bridging continuous glucose monitoring and insulin pump treatment, is counted among the most innovative systems to manage diabetes." (PMID 37569354, 2023). "Post-pancreatic diabetes was associated with poor glycemic control (adjusted odds ratio 1.7 (1.3–2.2); p < 0.001) compared with type 2 diabetes, and insulin use over 5 years was 20.9% (14.6–28.9) with diabetes after acute pancreatitis." (PMID 36979645, 2023). "Considering the gut microbiome, SCFAs have also been investigated as potential additives in the regular diet to positively influence insulin sensitivity, obesity, diabetes control, and immune modulation to counter autoimmune diseases." (PMID 38371896, 2023). "Diabetes Mellitus (DM) is characterized by chronic elevation of blood glucose levels due to insufficient insulin secretion from pancreatic β cells or the development of resistance in peripheral tissues to insulin or both." (PMID 36839674, 2023). "Pancreatic β-cell heterogeneity has been studied extensively using single cell technology because of the cell type’s unique insulin-secreting capabilities and central role in diabetes etiology." (PMID 36978008, 2023). "One such cytokine that gained attention over the years is adipokines such as adiponectin, resistin, and chemerin postulated in diabetes and periodontal diseases for their substantial effects on insulin sensitivity and inflammatory disease process respectively." (PMID 36751175, 2023). "More than 250,000 units of insulin made by this method were used in the treatment of diabetes patients with satisfactory results." (PMID 36585966, 2023). "The patient’s parents and brother did not exhibit hypokalemia, yet the patient’s mother had a 15-year history of diabetes, initiating insulin therapy during the fifth year of her diabetes diagnosis." (PMID 38333726, 2023). "Diabetes mellitus is a metabolic disease characterized by the inability of the body to produce or respond to the action of insulin." (PMID 37396152, 2023). "Our study is in agreement with many other studies, which concluded a significant correlation between the level of HbA1c and diabetes duration (poor glycemic control in patients with a duration of 6 years and more), adherence to dietary management, and insulin." (PMID 39296354, 2023). "A 27-year-old North African female patient with a history of diabetes mellitus and gastroduodenal ulcer was regularly taking subcutaneous insulin and proton pump inhibitors." (PMID 37980489, 2023). "There is evidence in the literature that NGF is also related to diabetes, a clinical condition that is also characterized by inflammatory processes playing an important role in glucose tolerance and insulin sensitivity dysregulation." (PMID 37373824, 2023). "In a study that collected data on 14 gamification practices of diabetes self-management, the avatar element was mainly used to simulate insulin injection and diet management to maintain normal blood sugar levels." (PMID 38133907, 2023). "Patients with diabetes and COVID-19 should be carefully monitored for their adherence to prescribed medications (including insulin injections) and their blood levels of glucose, which should be checked more frequently." (PMID 34328581, 2023). "Pig pancreatic extracts were used to treat diabetes until recombinant human insulin was commercialized in 1982." (PMID 37873836, 2023).